PGAM1 (phosphoglycerate mutase 1)
Diseases named in the same sentence as PGAM1 in open-access papers (continued):
Sharing a sentence is not in itself a finding about the gene and the disease.
cancer (continued). "Taken together, PGAM1 is a promising target for cancer treatment." (PMID 30818883, 2019). "In recent years, several studies have shown that PGAM1 levels are higher in several human cancers." (PMID 31240215, 2019). "Both of them showed moderate inhibition activity on PGAM1 and cancer cell proliferation." (PMID 30818883, 2019). "Furthermore, PGAM1 is upregulated in many kinds of tumors and the expression of PGAM1 is correlated with cancer patients’ prognosis." (PMID 30818883, 2019). "Therefore, we suggest that PGAM1 is a downstream effector of mTOR signaling and a potential target for cancer treatment." (PMID 29362480, 2018). "Inhibition of PGAM1 provides a new promising therapeutic strategy for cancer treatment." (PMID 29890679, 2018). "Accordingly, developing PGAM1 inhibitors could not only reduce the indispensable energy supply for cancer cells but also block the required anabolic processes including PPP and SSP, and hence provide a new dual-functional anticancer strategy." (PMID 29890679, 2018). "Thus, inhibition of PGAM1 is a promising strategy that targets both glycolysis and biosynthetic pathways for the treatment of cancer." (PMID 29362480, 2018). "The second putative mechanism is the phosphorylation of tyrosine 26 (Y26) residue of PGAM1, which may greatly enhance PGAM1 activity and can explain the finding that Y26 phosphorylation is commonly found in human cancers." (PMID 28076845, 2017). "Our results may provide valuable insights into computer-aided design of drugs that specifically target cancer cells with PGAM1 tyrosine 26 phosphorylated." (PMID 28076845, 2017). "Our studies have revealed considerable atomistic details of PGAM1, its substrates, and their interactions, which may provide valuable insights into computer-aided design of drugs that specifically target cancer cells." (PMID 28076845, 2017). "Hence, targeting PGAM1, which may limit both glycolysis and its shunts, is considered as a killing-two-birds-with-one-stone strategy for cancer therapy." (PMID 38750259, 2024). "However, the mechanistic role of PGAM1 methylation in cancer has been unclear." (PMID 38434965, 2024). "Therefore, elucidating the role of PGAM1 in tumor metabolism and other biological processes could contribute to evaluating its potential as a therapeutic target for cancer treatment." (PMID 38434965, 2024). "This implies that hypomethylation of PGAM1 may promote the development of various cancers." (PMID 38434965, 2024). "In addition, studies have shown the involvement of PGAM1 in cancer progression." (PMID 37542027, 2023). "Therefore, our results revealed an in-depth and comprehensive mode of action of PGAM1 in cancers." (PMID 37542027, 2023). "Inhibiting PGAM1 activity or targeting its downstream signaling pathways may represent a promising approach to disrupt tumor metabolism, enhance chemosensitivity, and modulate immune responses in cancer." (PMID 37338518, 2023). "Moreover, in PCa, PGAM1 secreted by exosomes induces cancer progression." (PMID 37542027, 2023). "Phosphoglycerate mutase 1 (PGAM1), an enzyme that catalyzes the mutual conversion of 2-phosphoglycerate and 3-phosphoglycerate during glycolysis, is commonly upregulated in various human cancers and plays an important role in regulating anabolic activity and glycolysis to promote tumor development." (PMID 36276846, 2022). "Therefore, PGAM1 has been considered as a treatment target of cancers." (PMID 36077431, 2022). "Therefore, the design and development of novel small molecules with an anthraquinone core targeting PGAM1 may prove to be an effective strategy for the treatment of cancer cells." (PMID 34899321, 2021). "Thus, PGAM1 is considered to be an emerging target for cancer treatment." (PMID 34899321, 2021).
cancer (continued). "The phosphoglycerate mutase 1 (PGAM1) is another downstream target of Akt with important metabolic functions; however, PGAM1 not only regulates glycolysis, but also PPP and serine biosynthesis, and is associated with proliferation, metastasis and survival of cancer cells." (PMID 33202866, 2020). "PGAM1 is thus a downstream effector of mTOR signaling pathway and mTOR-PGAM1 signaling cascade may contribute to the development of Warburg effect observed in cancer." (PMID 29362480, 2018). "Future research should validate their roles in brain metastases across other cancer types and explore the broader metabolic and immune regulatory networks involving SEC61G and PGAM1." (PMID 39990664, 2025). "The succinylation of PGAM1 by HAT1 seems to play a critical role in promoting tumor progression in vitro and in vivo in various types of cancer, including PDAC." (PMID 38785507, 2024). "Central carbon metabolism in cancer-related genes, i.e., SLC16A3, FGFR3, LDHA, PGAM1, and SLC2A1, significantly reduced after treatment with CTPPPPD." (PMID 39275122, 2024). "Additionally, PGAM1 expression positively correlated with infiltration levels of numerous immune cells including CD4+ T cells, CD8+ T cells, regulatory T cells, macrophages, natural killer cells, myeloid dendritic cells, monocytes and cancer-associated fibroblasts in UVM." (PMID 38434965, 2024). "Cancer-related biological processes such as EMT, apoptosis, and immune response were significantly activated in PGAM1-high UVM patient samples, as shown by GSEA enrichment analysis." (PMID 38434965, 2024). "In this study, we systematically evaluated the methylation level of PGAM1 in the UALCAN database and found that the methylation level of PGAM1 was significantly reduced in eight cancer types." (PMID 38434965, 2024). "PGAM1 is an oncogene that activates the TGF-β signaling pathway in NSCLC to increase the proliferation and invasion of cancer cells." (PMID 39275122, 2024). "Most of them exhibit high potency against PGAM1 as compared to PGMI-004A and their anti-proliferation activity was moderate on different cancer cell lines." (PMID 37051414, 2023). "One of the listed PGAM1 inhibitors is MJE3, but there are very limited scientific reports about its anti-cancer activity." (PMID 35628385, 2022). "GBM tumors displayed distinct Warburg-like genetic features, with increased HK2, PGAM1, ALDOC, and PGK1 expression that facilitates lactate production and confers resistance to hypoxic stress in cancer cells." (PMID 35004842, 2021). "The Phosphoglycerate mutase 1 (PGAM1) is a key glycolytic enzyme that coordinates different metabolic process including glycolysis, PPP, and serine biosynthesis in cancer cells." (PMID 33834022, 2021). "Phosphoglycerate mutase 1 (PGAM1), a key aerobic glycolysis enzyme in cancer metabolism, dynamically converts 3-phosphoglycerate (3-PG) to 2-phosphoglycerate (2-PG), which regulates glycolysis, pentose phosphate pathway (PPP) flux, and biosynthesis." (PMID 34689761, 2021). "For example, PGAM1 activity directly regulates the PPP and the resulting production of nucleotides, promoting cancer cell proliferation and tumor resistance to conventional therapies." (PMID 33834022, 2021). "The highest glycolysis score, PGK1 and PGAM1 mRNA abundance were observed under high hypoxia and high HSPA8 expression across cancer types." (PMID 32635458, 2020). "Phosphoglycerate mutase 1 (PGAM1) coordinates glycolysis and biosynthesis to promote cancer cell proliferation, and is believed to be a promising target for cancer therapy." (PMID 30818883, 2019).
cancer (continued). "For MMP9 and PGAM1, both normal (OK113) and cancer (SqCC/Y1) exosomes triggered dose-dependent upregulation of MMP9 and PGAM1, but cancer exosomes were significantly more potent than normal exosomes." (PMID 30008265, 2018). "Upon further dose- and time-dependent exosome transfection experiments validation by qRT-PCR, we found that cancer exosomes induced stronger upregulation of MMP9 and PGAM1 whilst suppressed BBOX1 and EFEMP1, compared to normal exosomes." (PMID 30008265, 2018). "Phosphoglycerate mutase 1 (PGAM1) is a glycolytic enzyme that importantly coordinates glycolysis, pentose phosphate pathway (PPP) flux and serine biosynthesis in cancer cells and hence gains increasing interest of inhibitor discovery." (PMID 28611670, 2017). "In summary, the enzymatic inhibition of PGAM1 by EGCG brought us new biochemical and pragmatic insights into targeting aerobic glycolysis for cancer therapy." (PMID 28611670, 2017). "Phosphoglycerate mutase 1 (PGAM1) catalyzes the eighth step of glycolysis and is often found upregulated in cancer cells." (PMID 28076845, 2017). "As a result of these studies, novel biomarkers for cancer diagnosis [e.g. stathmin 1 (STMN1), transgelin 2 (TAGLN2)] or potential targets for therapeutic intervention were proposed (e.g. phosphoglycerate mutase 1 (PGAM1))." (PMID 29050215, 2017). "Particularly, dual inhibitors of PGAM1 and 6-PGDH (e.g., PGMI-004A) and inhibitors of the relatively cancer-specific target PFK-FB3 such as PFK15 warrant further investigation." (PMID 27418963, 2016). "Given the importance of PGAM1 in cancer progression, it is not surprising that PGAM1 is intricately regulated by multiple factors at the transcriptional, translational, and post-translational levels." (PMID 38773094, 2024). "Given the importance of PGAM1 in regulating cancer metabolism, the expression and activity of PGAM1 are not surprisingly controlled at different levels." (PMID 38773094, 2024). "Here, PGAM1 activity is shown to be controlled by pyruvate kinase M2 (PKM2), promoting glycolytic shunts and macromolecule biosynthesis during metabolic reprogramming in cancer cells." (PMID 38750259, 2024). "For example, by modulating Bcl-2, PGAM1 could influence apoptotic pathways, while its interaction with Snail could impact the EMT process, a critical step in cancer metastasis." (PMID 38434965, 2024). "This non-enzymatic activity of PGAM1 highlights its potential as a theranostic target in cancer treatment strategies." (PMID 38434965, 2024). "The role of PGAM5 in cancer is not as extensively studied as PGAM1, but it is emerging as an important player in cancer cell biology." (PMID 37847178, 2023). "Moreover, a study has shown that PGAM1 interacts with ACTA2 (unrelated to its metabolic activity) to promote actin filaments assembly, cancer cell migration, and cell motility." (PMID 37542027, 2023). "PGAM1 and ENO1 are overexpressed in different cancers, while their inhibition may result in decreased tumor growth and metastasis." (PMID 37500057, 2023). "PGAM1 and ENO1 are important glycolytic enzymes that catalyze the conversion of 3-phosphoglycerate to phosphoenolpyruvate and coordinate glycolysis and biosynthesis that are important in cancer progression." (PMID 37500057, 2023). "Studies have shown that the glycolytic enzymatic activity of PGAM1 plays a role in cell proliferation, whereas the non-metabolic activity of PGAM1 plays a role in the migratory and invasive abilities of cancer cells." (PMID 37542027, 2023). "Previous studies have shown the involvement of the glycolytic enzymatic activity of PGAM1 in cell proliferation, whereas the non-metabolic activity of PGAM1 plays a role in the migration and invasion of cancer cells." (PMID 37542027, 2023). "PGAM1, PGAM4, and NOL6 have been reported to be tumorigenic in several cancers." (PMID 37667226, 2023).
cancer (continued). "In addition to PGAM1, another subfamily of PGAM enzymes, PGAM5, has also been shown to regulate several aspects of cancer cell death, including apoptosis and necrosis, by altering mitochondrial function." (PMID 37847178, 2023). "Therefore, elevated glycolytic enzyme phosphoglycerate mutase 1 (PGAM1) keeps its substrate 3-PG to a relatively low level and promotes the PPP in cancer cells." (PMID 32582032, 2020). "We consider PGAM1 as a novel prognostic biomarker for NSCLC and a therapeutic target for cancer." (PMID 29362480, 2018). "Of note, our recent studies have also revealed that PGAM1 inhibition inactivated homologous recombination repair and exhibited synthetic lethality with PARP inhibitors in cancer cells, which further inspired the interest to develop PGAM1 inhibitors for the treatment of cancer." (PMID 28611670, 2017). "Likewise, inhibitors of phosphoglycerate mutase 1 (PGAM1) and mutant isocitrate dehydrogenase (IDH), both catalases involved in glycolysis in cancer cells, are considered to be promising candidates as cancer drugs." (PMID 26375553, 2015). "Additionally, intense expression of PGAM1, HSPD1, and PDIA3 was observed in the cytoplasm of cancer cells in both hilar and intrahepatic CC." (PMID 23118872, 2012). "Similarly, HAT1 (histone acetyltransferase 1), which succinylates H3K122, contributing to epigenetic gene regulation in cancer cells and PGAM1 (Phosphoglycerate Mutase 1) in a non-histone region, stimulates glycolytic fluxes in cancer cells." (PMID 35631199, 2022). "PGAM1 is a glycolytic enzyme that dynamically converts 3-phosphoglycerate (3PG) to 2-phosphoglycerate (2PG) and is upregulated to coordinate serine biosynthesis, pentose phosphate pathway (PPP), and glycolysis to regulate tumor and cell proliferation in cancer." (PMID 34195264, 2021). "To prove whether PGAM1 inhibition contributed to the anticancer activity of EGCG, we compared its anticancer activity in a pair of cancer cells with or without PGAM1 depletion." (PMID 28611670, 2017). "In addition, we analyzed the correlation between PGAM1 and methylation-related genes, and the results showed that PGAM1 had significant correlations with methyltransferases such as DNMT1, DNMT3A and DNMT3B as well as methylation modifications such as m1A, m5C and m6A across various cancers." (PMID 38434965, 2024). "Similar to many metabolic enzymes, PGAM1 asserts a nonenzymatic function, as the physical interaction with checkpoint kinase 1 (Chk1) increases proliferation, specifically in RAS-driven cancer cells." (PMID 36139550, 2022).
tumor (90 papers, 2010 to 2026). "Another study revealed that PGAM1 is a critical regulator of mTOR-mediated tumour growth and is associated with aggressive NSCLC phenotypes." (PMID 41154605, 2025). "Phosphoglycerate mutase 1 (PGAM1), a key enzyme in the glycolytic pathway, is closely associated with tumour cell proliferation and survival." (PMID 40337517, 2025). "Several IHC studies on NSCLC tissues also reported that PGAM1 was significantly overexpressed compared to adjacent normal lung tissues, and associated with poor prognosis, increased tumour growth, and enhanced metastatic potential." (PMID 41154605, 2025). "For example, the ability of aspirin to limit tumor proliferation is associated with its capacity to reduce the succ level of PGAM1." (PMID 39278916, 2024). "The results indicate prominent expression of PGAM1 in both immune cells, especially tumor-associated macrophages, and in malignant cells." (PMID 38434965, 2024). "We found that the expression of PGAM1 in a variety of solid tumors was significantly higher than that in normal tissues and was closely associated with tumor progression and clinical prognosis." (PMID 38434965, 2024). "Phosphoglycerate mutase 1 (PGAM1) is a crucial glycolytic enzyme, and its expression status has been confirmed to be associated with tumor progression and metastasis." (PMID 35674458, 2022). "In the present study, we demonstrated that PGAM1 was significantly upregulated in tumor tissues and associated with poor clinical prognosis of NSCLC." (PMID 32855383, 2020). "Functionally, gain- and loss-of-function analysis showed that PGAM1 promoted proliferation and invasion in vitro, and facilitated tumor growth in vivo." (PMID 32855383, 2020). "Its encoded cytoskeletal protein can interact with phosphoglycerate mutase 1, regulate the assembly of cellular actin filaments, control the contractile activity of tumor cells and fibroblasts, and regulate tumor metastasis." (PMID 32786144, 2020). "Moreover, we identified macrophages as key contributors to PGAM1 upregulation in tumor tissues, and analysis of spatial transcriptome and single-cell sequencing showed that PGAM1 expression is associated with immune TIME." (PMID 37847178, 2023). "Moreover, 2‐DG and 3‐BP, as well as SLC2A3 and PGAM1 down‐regulation, reversed the acceleration of tumor growth caused by METTL14 knockdown." (PMID 36794620, 2023). "Additionally, high PGAM1 expression was strongly associated with tumor size, macroscopic tumor thrombus, microvascular invasion and BCLC stage." (PMID 37705495, 2023). "Indeed, our study validated that the high expression of ASS1 caused by the knockdown of PGAM1 reduced the proliferation of tumor cells in vitro, and alleviated tumor growth in xenograft models." (PMID 35674458, 2022). "Furthermore, PGAM1 has been reported to be associated with proliferation, migration, and apoptosis of tumor cells and its enzymatic activity." (PMID 34195264, 2021). "However, its linear splicing variant, PGAM1, has been confirmed to influence aerobic glycolysis in tumor cells to exert a tumor‐promotion function in some tumors." (PMID 32167655, 2020). "Similarly, increments in ENOA and PGAM1 have been associated with tumor proliferation, cell migration, and apoptosis." (PMID 28719635, 2017). "Moreover, PGAM1 has been implicated in promoting cell proliferation and tumor growth." (PMID 37338518, 2023). "This interaction was explored in cell lines and the loss of PGAM1 was shown to decrease the effects of hypoxia on the tumor by inhibiting the ability of the cell to regulate balance between glycolysis and biosynthesis allowing tumor growth that would be inhibited in a hypoxic state." (PMID 27716027, 2016). "PGAM1 promotes glycolytic metabolism, facilitating ATP production and biosynthetic processes essential for rapid tumour cell proliferation." (PMID 41154605, 2025).